CXCR3 (C-X-C motif chemokine receptor 3)
Diseases named in the same sentence as CXCR3 in open-access papers (continued):
Sharing a sentence is not in itself a finding about the gene and the disease.
chronic lymphocytic thyroiditis (1 paper, 2022). "Myeloid cells express chemokines (CXCL12 and CXCL10) as chemoattractants to recruit T cells expressing their receptors (CXCR4 and CXCR3), which is consistent with the pathological findings indicating chronic lymphocytic thyroiditis in P1 and P2 patients." (PMID 35515000, 2022). "Myeloid cells expressed genes (CXCL10 and CXCL12) for chemokines as chemoattractants to recruit T cells expressing CXCR4 and/or CXCR3 in T1 and T2 samples, but not in T3, which was in accordance with the histological assessment that indicated chronic lymphocytic thyroiditis in T1 and T2 samples." (PMID 35515000, 2022).
CNS lymphoma (1 paper, 2024). "Therefore, future studies should investigate in detail the role of IP-10/CXCR3 in promoting tumor-specific T cell responses, especially in patients with CNS lymphoma." (PMID 38349430, 2024).
colon adenocarcinoma (1 paper, 2022). "According to the bioinformatics analysis in this study, the infiltration of macrophages, especially M2 macrophages, positively correlates with CgA and CXCR3 gene expression, respectively, in colon adenocarcinoma." (PMID 36030223, 2022). "In this study, we further illustrated that exosome-derived lnc-HOXB8-1:2 induced the migration and invasion of TAMs to promote the development of colon adenocarcinoma with neuroendocrine differentiation via sponging hsa-miR-6825-5p to upregulate CXCR3 expression." (PMID 36030223, 2022). "However, if CXCR3 plays a vital role in antitumor immune infiltration, why is CXCR3 expression on TAMs increased and correlated with tumor progression in neuroendocrine differentiated colon adenocarcinomas?" (PMID 36030223, 2022).
colorectal adenocarcinoma (1 paper, 2022). The most common type of colorectal carcinoma. "Both the infiltration of macrophages and M2 macrophages were proportional to the CXCR3 gene expression level in most colorectal adenocarcinomas, while some results were contrary." (PMID 36030223, 2022).
corneal infection (1 paper, 2011). A viral or bacterial infectious process affecting the cornea. "Mice received a single subcutaneous injection of TAK-779 at 6 dpi to inhibit the activity of both CXCR3 and CCR5 during the initial CD8+ T cell infiltration of the TG that occurs 6-8 days after HSV-1 corneal infection." (PMID 21429183, 2011).
coronary artery calcification (1 paper, 2018). Calcification of the coronary artery, used as a measure of coronary atherosclerosis, a risk factor for myocardial infarction. "CXCL9 and other CXCR3 chemokines have been implicated in the regulation of migration of monocytes and lymphocytes and their retention in atherosclerotic lesions, and serum levels of CXCL9 correlate with severity of coronary narrowing as well as coronary artery calcification." (PMID 30563576, 2018).
cutaneous melanoma (1 paper, 2014). A primary melanoma arising from atypical melanocytes in the skin. "The expression of CXCR3 has been observed in patients with primary invasive cutaneous melanomas and there is a significant association of CXCR3-positive tumor cell immunostaining with tumor thickness >1 mm." (PMID 24559071, 2014).
cutaneous T-cell lymphomas (1 paper, 2025). "CXCR3 is notably downregulated in erythrodermic cutaneous T-cell lymphomas, including Sézary syndrome." (PMID 40861461, 2025).
cystinosis (1 paper, 2024). Cystinosis is a metabolic disease characterized by an accumulation of cystine inside the lysosomes, causing damage in different organs and tissues, particularly in the kidneys and eyes. "Increase in CXCR3 and MCP-1 in cystinosis has not been previously reported to our knowledge." (PMID 39540998, 2024).
delirium (1 paper, 2025). A disorder characterized by confusion; inattentiveness; disorientation; illusions; hallucinations; agitation; and in some instances autonomic nervous system overactivity. "Other cell types showed correlations primarily with delirium, such as memory CD4 + T cells expressing CXCR3, activated T cells, IgM + unswitched memory B cells, and exhausted B cells (CD21low CD38low)." (PMID 41219650, 2025).
dementia (1 paper, 2023). Loss of intellectual abilities interfering with an individual's social and occupational functions. "Moreover, neural hyperexcitability has been reported in dementia, and global KO of CXCR3 prevents memory deficits in transgenic mice with amyloid-β pathology." (PMID 37075107, 2023).
demyelinating disease (1 paper, 2012). A broad group of disorders that affect the myelin sheaths that cover the neurons. "In contrast to MOG-EAE, CXCR3 appears to promote the lymphocyte accumulation inside the CNS in some virus-induced demyelinating disease models." (PMID 22233170, 2012).
Dry skin (1 paper, 2021). Skin characterized by the lack of natural or normal moisture. "However, the inhibitory effects of paeonol on these genes was abolished in CXCR3-deficient mice, supporting that paeonol relieved the pruritus of dry skin mice by inhibiting the spinal astrocytic activation driven by CXCR3." (PMID 35095512, 2021). "Results of RT-qPCR and western blotting demonstrated that both mRNA and protein levels of CXCR3 gradually elevated in the spinal cord of AEW mice, suggesting that CXCR3 was likely involved in the pathogenesis of dry skin." (PMID 35095512, 2021). "Similarly, though paeonol significantly impaired the scratching frequency in AEW-induced C57BL/6J mice, it was almost ineffective in Cxcr3−/− mice stimulated by AEW, demonstrating that spinal CXCR3 was indispensable for the anti-pruritic activity of paeonol in AEW-induced dry skin." (PMID 35095512, 2021). "Reactive astrocytes in the SDH have been reported in models of dry skin and activated astrocytes may produce CXCR10 to act on neurons through CXCR3 via a paracrine signaling." (PMID 35095512, 2021). "Absence of the chemokine receptor CXCR3 inhibited both astrocytic activation and chronic itch in AEW-induced dry skin model mice." (PMID 35095512, 2021).
dysplasia (1 paper, 2021). A usually neoplastic transformation of the cell, associated with altered architectural tissue patterns. "The transcript levels of Th1-associated chemokines/cytokines (Cxcl9, Cxcl10, Ccl5, and Ifng) and the Th1-associated chemokine receptor Cxcr3 were upregulated in dysplasia, whereas the expression of these Th1-associated genes was decreased in SCC." (PMID 33921389, 2021).
eating disorder (1 paper, 2022). A broad group of psychological disorders with abnormal eating behaviors leading to physiological effects from overeating or insufficient food intake. "After refeeding during 6 weeks of multimodal therapy, CXCR3 levels normalized on CD4+ T cells in AN suggesting that this immune alteration is linked to the pathophysiology of this eating disorder." (PMID 36226111, 2022).
eczema (1 paper, 2017). "In skin lesions from eczema, the mean percentages of inflammatory cells expressing CXCL9, CXCL10, CXCL11 and CXCR3 were 4.8% ± 5.8%, 5.2% ± 6.3%, 63.2% ± 15.7% and 25.2% ± 13.0%, respectively." (PMID 28436448, 2017).
endometrial adenocarcinoma (1 paper, 2023). "Nevertheless, in our study, the qPCR result showed that the relative expression of CXCR3 in endometrial adenocarcinoma was lower than in normal endometrium." (PMID 36750966, 2023). "The expression of CXCR3 was tested by qPCR with clinical samples from adenocarcinoma patients and normal endometrium from patients with other diseases that need to remove the uterus to identify the effect of CXCR3, indicating that the expression of CXCR3 was lower in endometrial adenocarcinoma." (PMID 36750966, 2023). "In endometrial adenocarcinoma, CXCR3 was identified as a meaningful anti-tumor gene." (PMID 36750966, 2023). "We also developed and validated a predictive nomogram model combining CXCR3, age, histological grade, and FIGO stage for endometrial adenocarcinoma, which could help explore the precise treatment." (PMID 36750966, 2023).
endotoxemia (1 paper, 2023). "To further characterize the role of IP-10–CXCR3 in lung injury in the context of endotoxemia, we performed histopathological evaluation with a neutralizing Ab against IP-10 and Cxcr3-deficient mice." (PMID 37701855, 2023). "MRP8/14 induces sustained IP-10 production by activating the IFNβ-JAK1/TYK2-STAT1-IRF7 pathway, which subsequently attracts numerous CXCR3+ T cells and results in an exaggerated inflammatory response and lung injury in the context of endotoxemia." (PMID 37701855, 2023). "In vivo air pouch experiments confirmed that the IFNβ-JAK1/TYK2-STAT1-IRF7 pathway was required for chemokine (C-X-C motif) receptor 3 (CXCR3)+ T lymphocyte migration, which promoted lung injury in the context of endotoxemia." (PMID 37701855, 2023). "Prolonged production of IP-10 attracts CXCR3+ lymphocytes to lung tissues and triggers an exaggerated inflammatory response and lung injury during endotoxemia via the IFNβ–IRF7 axis." (PMID 37701855, 2023). "In summary, our study demonstrates that MRP8/14 induces sustained production of IP-10 via the IFNβ-JAK1/TYK2-STAT1-IRF7 pathway to attract CXCR3+ T lymphocytes into lung tissues and ultimately results in lung injury by an excessive inflammatory response in the context of endotoxemia." (PMID 37701855, 2023).
enteropathy (1 paper, 2014). "Because Th1 cells characteristically express CXCR3 and certainly take part in the damage mechanisms that cause severe enteropathy, the aim of this work was to assess the role of the CXCL10/CXCR3 axis in lymphocytic recruitment in active CD." (PMID 24586509, 2014).
Fabry disease (1 paper, 2024). Fabry disease (FD) is a progressive, inherited, multisystemic lysosomal storage disease characterized by specific neurological, cutaneous, renal, cardiovascular, cochleo-vestibular and cerebrovascular manifestations. "Moreover, studies observed an increase in blood lymphocyte counts, with notable elevations in specific T cytotoxic cell subsets (CCR4+CXCR3+ and CCR6+), as well as the presence of MHCII+ CD1d+ CD11b+ CD31+ monocytes in patients with Fabry disease." (PMID 39596318, 2024). "Furthermore, patients with Fabry disease exhibit elevated blood lymphocyte counts, increased levels of specific T cytotoxic cell subsets (CCR4+CXCR3+ and CCR6+), higher numbers of MHCII+ CD1d+ CD11b+ CD31+ monocytes, and notable tissue infiltration by macrophages and B cells." (PMID 39596318, 2024).
falciparum malaria (1 paper, 2024). "Inflammatory environments and cytokine milieu can induce Tfh cells to differentiate into different subsets as it was shown in acute falciparum malaria that IFN-γ cytokine responses preferentially activated CXCR3+ Tfh cells." (PMID 39475899, 2024).
fungal keratitis (1 paper, 2023). "We identified several specific genes and pathways involved in the host response to infectious keratitis, including CXCL9, CXCR3, and MMP9 for viral, and S100A8/A9, MMP9, and the IL17 pathway for bacterial/fungal keratitis." (PMID 38274739, 2023). "We identified several genes and pathways involved in the host response to infectious keratitis, including CXCL9, CXCR3, and MMP9 for viral, and S100A8/A9, MMP9, and the IL17 pathway for bacterial/fungal keratitis." (PMID 38274739, 2023).
Genital ulcers (1 paper, 2017). "Third, we could not examine oral ulcer and genital ulcer biopsies from BD patients for CXCR3 expression." (PMID 29116188, 2017).
glomerulosclerosis (1 paper, 2025). A hardening of the kidney glomerulus caused by scarring of the blood vessels. "In mice with acute glomerular inflammation, genetic deletion of CXCL11 receptor Cxcr3 attenuates glomerulosclerosis and albuminuria." (PMID 40485680, 2025).
Glucose intolerance (1 paper, 2024). Glucose intolerance (GI) can be defined as dysglycemia that comprises both prediabetes and diabetes. "The inhibition of CXCR3 resulted in increased body mass gain, worsening of glucose intolerance, and increased mRNA expression of hypothalamic Npy." (PMID 39535032, 2024). "Systemic chemical inhibition of CXCR3 led to significant metabolic changes, including increased body mass, reduced energy expenditure, elevated blood leptin, glucose intolerance, and decreased insulin levels." (PMID 39535032, 2024).
HCMV infection (1 paper, 2021). "The association of persistent HCMV infection with vascular disease could also be partly explained by recruitment of activated T cells to peripheral sites of latency, as demonstrated here, as it is long established that CXCR3 expressing CD4+ T cells are recruited to atherosclerotic plaque sites." (PMID 33912186, 2021).
head and neck squamous cell carcinoma (1 paper, 2022). A squamous cell carcinoma that arises from any of the following anatomic sites: lip and oral cavity, nasal cavity, paranasal sinuses, pharynx, larynx, and salivary glands. "The combination of cisplatin and cGAMP showed effective CXCR3-dependent antitumor effects in a mouse model of head and neck squamous cell carcinoma (HNSCC)." (PMID 36353640, 2022).
Hyperinsulinemia (1 paper, 2024). An increased concentration of insulin in the blood. "Accordingly, hyperinsulinemia maintained its immunosuppressive effect in CD4+ cells of the JAKi-treated patients by mitigating upregulation of the key Th1 transcription factors RORC and PRDM1, as well as the chemokine receptors CXCR3 and CCR5." (PMID 39768214, 2024).
IgA nephropathy (1 paper, 2024). "The basic anti-CXCR3 antibodies correlated with the creatinine level after 2 years in the IgA nephropathy group (p = 0.01)." (PMID 39768675, 2024). "Nevertheless, the influence of anti-CXCR3 antibodies on the course of FSGS and IgA nephropathy cannot be excluded and should be checked using bigger groups of patients who are divided into subgroups according to the dosage of ACE inhibitor received." (PMID 39768675, 2024).
IgA vasculitis (1 paper, 2024). "Recruitment of CXCR3+ T-cells in the kidney of adult patients with IgA vasculitis correlates with the involvement of the CX3CR1–fractalkine axis in the exacerbation of gross hematuria." (PMID 38791337, 2024).
infarction (1 paper, 2018). A localised pathological necrosis of tissue resulting from obstruction of the blood supply usually by a thrombus, an embolus, or vascular torsion. "Although CXCR3 is well-known to activate pro-inflammatory Th1 lymphocyte responses, deficiency of CXCR3 did not affect post-infarction cardiac remodeling." (PMID 30210493, 2018).
infectious keratitis (1 paper, 2023). "Along these lines, mice that are deficient in CXCR3, the receptor for CXCL9, have less severe keratitis, indicating that the CXCL9 receptor is also a critical mediator of the pathological immune response in viral keratitis." (PMID 38274739, 2023).
infertile (1 paper, 2017). "We observed a slight increase CXCR3, CX3CR1 and CCR2 receptors in eNK cells from infertile women positive for HHV-6A infection (p = 0.02; p = 0.012; p = 0.01, respectively; Student’s t-test)." (PMID 29326672, 2017).
intracranial aneurysm (1 paper, 2021). "In this study, we investigated thepotential biological effects of miR-34a and its target CXCR3 in phenotypicmodulation of vascular smooth muscle cells (VSMCs) of intracranial aneurysms(IAs)." (PMID 33901269, 2021).
intrauterine growth restriction (1 paper, 2023). "CXCR3 interacts with its ligands to disrupt fetal-maternal immune tolerance, triggering a range of chronic inflammatory lesions in the placenta that lead to intrauterine growth restriction, fetal death, spontaneous abortion, premature rupture of membranes, and preterm delivery." (PMID 37033160, 2023).
ischemia reperfusion injury (1 paper, 2014). Adverse functional, metabolic, or structural changes in ischemic tissues resulting from the restoration of blood flow to the tissue (reperfusion), including swelling; hemorrhage; necrosis; and damage from free radicals. "While the treatment of CXCR3-deficient mice with concanavalin A results in a decreased recruitment of IL10-producing CXCR3+ Tregs, CXCR3 blockade in a model for ischemia-reperfusion injury causes a reduction in intrahepatic Th1 cells." (PMID 24646914, 2014).
kidney tumours (1 paper, 2003). "It will be interesting to determine whether the shared receptor for these molecules, CXCR3, which is expressed on activated T cells is also expressed on the vascular endothelial cells within the tumours, as has recently been shown for human kidney tumours." (PMID 12778077, 2003).
leprosy (1 paper, 2025). Leprosy is a chronic infectious disease affecting primarily the skin and peripheral nervous system. "Contacts of patients with leprosy are mainly associated with CXCR3/CCR4/HLA-DR and LL/BL patients with %B-06 (IgD+) and CCR6/CCR7." (PMID 40683203, 2025).
lichen sclerosus et atrophicus (1 paper, 2008). A chronic inflammatory process affecting the skin. "For example, lichen sclerosus et atrophicus or white-spot disease is a chronic inflammatory skin disease where CXCR3+ cytotoxic T cells are involved in its pathogenesis." (PMID 18957084, 2008).
limited cutaneous systemic sclerosis (1 paper, 2018). Limited cutaneous systemic sclerosis (lcSSc) is a subtype of systemic sclerosis (SSc) characterized by the association of Raynaud's phenomenon with skin fibrosis limited to the hands, face, feet and forearms. "Anti-CXCR3 ab levels were higher in patients with diffuse cutaneous systemic sclerosis (dSSc) compared with patients with limited cutaneous systemic sclerosis (lSSc) (p ≤ 0.001) and HD (p ≤ 0.001); 17.6% of the dSSc patients revealed anti-CXCR3 ab levels above the 95th percentile." (PMID 29566745, 2018).
Löfgren’s syndrome (1 paper, 2023). "Interestingly, patients with Löfgren’s syndrome had increased levels of T-bet+ RORγt+ cells that produced IFN-γ and IL-17 A, co-expressed the chemokine receptors CXCR3 and CCR6, and their frequencies correlated with nonchronic disease." (PMID 37189479, 2023).
lupus erythematosus (1 paper, 2009). An autoimmune, connective tissue chronic inflammatory disorder affecting the skin, joints, kidneys, lungs, heart, and the peripheral blood cells. "CXCL10 has been associated with Th1 type responses in several clinical systems recruiting CXCR3+ effector lymphocytes from the peripheral blood into lupus erythematosus skin lesions, and into inflammatory lesions of the central nervous system." (PMID 19473542, 2009).
lymphedema (1 paper, 2023). Excess fluid collection in tissues, causing swelling. "High percentages of PD-L1+CXCR3+ and PD-1+CXCR3+ lymphocytes were associated with high LDH levels, hepatomegaly, lymphedema, advanced tumor stage, and recurrence." (PMID 36726488, 2023).
male infertility (1 paper, 2017). The inability of the male to effect fertilization of an ovum after a specified period of unprotected intercourse. "The CXCL10/CXCR3 system in testicular cells might be considered as a therapeutic target for male infertility caused by MuV infection." (PMID 29072682, 2017).
mantle cell lymphoma (1 paper, 2022). Mantle cell lymphoma is a rare form of malignant non-Hodgkin lymphoma affecting B lymphocytes in the lymph nodes in a region called the ``mantle zone''. "Tumors with high CXCR3 expression are prone to cancer cell proliferation and infiltration, both in CRC and mantle cell lymphoma, although the mechanism leading to elevated levels of CXCR3 remains unknown." (PMID 36030223, 2022).
membranous nephropathy (1 paper, 2024). "An influence of ETAR antibodies on the course of membranous nephropathy, and CXCR3 antibodies on the course of FSGS, is also probable." (PMID 39768675, 2024). "Anti-ETAR antibodies appear to be connected with the prognosis of membranous nephropathy, and anti-CXCR3 antibodies may also be a marker of the course of FSGS." (PMID 39768675, 2024).
mental disorder (1 paper, 2022). A disease that has its basis in the disruption of mental process. "The CXC chemokine receptor CXCR3 controls CXCL9, CXCL10, and CXCL11 induced leucocyte trafficking to inflammatory sites, and reduced CXCR3 expression on CD4+ T cells and CXCR3+ CD4+ T cell numbers have been found in mental disorders." (PMID 36226111, 2022).